CYP3A4 (cytochrome P450 family 3 subfamily A member 4)
Diseases named in the same sentence as CYP3A4 in open-access papers (continued):
Sharing a sentence is not in itself a finding about the gene and the disease.
Stroke (14 papers, 2016 to 2025). Sudden impairment of blood flow to a part of the brain due to occlusion or rupture of an artery to the brain. "The co-administration of DOACs and inducers of P-gp and CYP3A4 may therefore reduce the bioavailability or increase the clearance of DOACs, with the potential to increase the risk of stroke and thromboembolism." (PMID 37122531, 2023). "A recent case–control retrospective study has shown that DDIs involving DOACs were linked to an increased risk of bleeding when associated with combined P-gp/CYP3A4 inhibitors and were linked to a higher risk for stroke and systemic emboli when associated with CYP3A4 inducers." (PMID 35890305, 2022). "The incidence rates of recurrent stroke/TIA events in both CYP3A4 and P-GP DDIs, P-GP DDIs only, and no DDIs were 7.5, 2.1, and 8.4/100 person-years, respectively." (PMID 33732201, 2020). "Surprisingly, we found that the use of CYP3A4 and/or P-GP inducers did not significantly alter the incidence of recurrent stroke/TIA even in patients who received underdosed NOACs despite the limited cohort size collected from a single institute." (PMID 33732201, 2020). "Compared to non-CYP3A4 metabolized statin plus clopidogrel, the CYP-3A4 metabolized statin therapy combined clopidogrel failed to reduce the incidence of stroke (RR 0.86; 95% CI 0.13,5.61; p = 0.875)." (PMID 31122249, 2019). "According to the data from the ROCKET AF study (Prevention of Stroke and Embolism Trial in Atrial Fibrillation), the presence of combined CYP3A4/5 and P-gp inhibitors did not have any impact on safety outcomes such as bleeding events when comparing the rivaroxabanand warfarin groups." (PMID 28066243, 2016). "However, for both stroke and major bleeding, estimates of RRs compared with warfarin were higher for patients with drugs affecting metabolism through CYP3A4 and P-gp than for patients without those drugs in the aggregated data and in separate analyses of apixaban and rivaroxaban." (PMID 33029651, 2021). "The use of inducers of CYP3A4 and/or P-gp was low in this cohort, and effects on ischemic stroke/TIA/stroke unspecified could not be established." (PMID 33029651, 2021).
cholestasis (13 papers, 2007 to 2025). Impairment of the bile flow caused by obstruction within the liver, or outside the liver in the bile duct system. "As for estrogen, cholestasis is associated with its elevated levels (in mice), whereas estrogen is involved in the regulation of CYP3A4 and suppresses its expression in humans." (PMID 36359206, 2022). "Differences in rates of cholestasis in women, especially caused by pregnancy, are thought to be attributed to differential regulation of CYP3A4." (PMID 31775872, 2019). "Liver cirrhosis associated with cholestasis is likely to modify the activity of CYP3A4." (PMID 19690646, 2007). "In diverse means, RIF triggers endoplasmic reticulum stress, which results in cholestasis, in addition to hepatic oxidative damage, bile acid accumulation, and CYP3A4 enzyme-induced toxic drug metabolites by pregnane X receptor (PXR)." (PMID 40851075, 2025). "Nevertheless, CYP3A4 activity can be stimulated early in cholestasis because bile acids can induce CYP3A4 expression indirectly through FXR and PXR." (PMID 36359206, 2022). "Genetic variations in the CYP3A4 could enhance CYP3A4 activity in cholestasis and increase detoxification." (PMID 39062040, 2024). "For instance, the implication of CYP3A4 stimulation in cholestasis could provide a novel therapeutic strategy." (PMID 39062040, 2024). "Stimulation of CYP3A4 activity in cholestasis may be an effective therapeutic approach to such diseases." (PMID 36359206, 2022). "CYP3A4 hydroxylates bile acids not only to increase their hydrophilicity, but also to increase their conjugation which exerts an essential protective mechanism in cholestasis in vivo." (PMID 32253466, 2020). "CYP3A4 is also responsible for protecting the liver against the toxic effects of high concentrations of BAs thereby serving as a master regulator of expression of many enzymes involved in BA synthesis to protect against cholestasis." (PMID 31775872, 2019). "Cancer and/or non-alcoholicfatty liver disease-related cirrhosis showed larger deteriorationin levels of CYP3A4, 2C8, 2E1, 1A6, UGT2B4/7, CES1, FMO3/5, EPHX1,MGST1/3, BSEP, and OATP2B1 than the cholestasis set." (PMID 34428046, 2021). "Furthermore, CYP3A4 may be adaptively up-regulated in cholestasis with unknown mechanism." (PMID 19690646, 2007). "The expression of CYP3A4 and CYP3A11 is increased in response to cholestasis." (PMID 39062040, 2024). "Moreover, despite the cholestasis and strong activation of nuclear receptors, we found no enhancement of the expression of the detoxification enzyme CYP3A4." (PMID 28008998, 2016).
liver failure (13 papers, 2012 to 2025). A liver disease characterized by the liver losing or has lost all of its function. "Nefazodone was withdrawn from the market because it was associated with hepatotoxicity and hepatic failure owing to the actions exerted over the cytochrome P450 (CYP3A4) and the complex I of the mETC, which increase the formation of reactive oxygen species." (PMID 35625717, 2022). "Alectinib is metabolized via CYP3A4, and it is known that in cases of liver failure, the blood concentration of alectinib can increase." (PMID 39527462, 2024). "Conversely, liver failure, renal failure, and the use of drugs that inhibit CYP3A4 may impair dexamethasone clearance." (PMID 23781306, 2012). "The published clinical pharmacokinetic studies suggest that liver failure can affect CYP1A2, CYP2C19, CYP2D6, CYP2E1 and CYP3A4 activities." (PMID 34575411, 2021). "Additionally, the impact of CYP2C19, CYP3A4, and CYP2C9 genes on hepatic insufficiency patients with IFI should be carefully considered." (PMID 37693307, 2023). "Our findings are contradictory to our hypothesis that liver failure would reduce the predominant metabolism of voriconazole by the cytochrome P450 enzymes (CYP), mainly CYP2C19 as well as CYP3A4 and CYP2C9." (PMID 34683408, 2021).
malaria (13 papers, 2014 to 2023). Malaria is a serious and sometimes fatal disease caused by a parasite that commonly infects a certain type of mosquito which feeds on humans. "The major finding includes: (i) CYP3A5 genotype has significant influence on plasma LF concentration and (ii) CYP3A4*1B is associated with malaria treatment outcome." (PMID 28673292, 2017). "The Co-administration of artemether lumefantrine (AL) with ciprofloxacin as treatment for malaria-typhoid co-infection is common in Nigeria and this increases risk of pharmacokinetic drug-drug interaction since ciprofloxacin is an inhibitor of CYP3A4 that metabolizes AL." (PMID 33490338, 2021). "Work is ongoing to verify DDI predictions in a virtual malaria population to account for changes in blood binding and CYP3A4 expression to incorporate this into our routine DDI strategy going forward." (PMID 37587640, 2023). "Recently, OZ439, a potent synthetic ozonide that is currently used for the treatment of uncomplicated malaria was found to inhibit CYP3A4 through both direct and mechanism-based inhibition." (PMID 36834793, 2023). "CYP3A4, CYP3A5 variants impact Lumefantrine response in a cohort of pregnant women with malaria in Tanzania." (PMID 32858798, 2020). "In general, the study finding indicates association of the low enzyme activity genotype of CYP3A4*5 and CYP3A4*1B with high LF plasma exposure and better malaria treatment outcome, respectively." (PMID 28673292, 2017). "This study reports an association study between the ABCB1 c.3435C>T, CYP3A4*1B (g.-392A>G), CYP3A5*3 (g.6986A>G) SNPs and artemether + lumefantrine treatment outcome in 103 uncomplicated malaria patients from Angola." (PMID 28934955, 2017). "For this purpose, functional variant alleles in CYP450 (CYP2B6, CYP3A4, CYP3A5) and ABCB1 genes involved in the metabolism of anti-malarial drugs were assessed in pregnant malaria patients treated with ALu." (PMID 28673292, 2017). "CYP2C8 along with CYP2B6, CYP3A4, and CYP3A5 metabolize drugs used in artemisinin-based combination therapy for malaria, and alleles such as CYP2C8*2, CYP2C8*3, CYP2B6*6, CYP3A4*1B, and CYP3A5*3 may affect patient response to this treatment." (PMID 36834793, 2023). "This may indicate that CYP3A5 plays a minor role compared to CYP3A4 in determining malaria treatment outcome." (PMID 28673292, 2017). "However, CYP3A4*1B did affect malaria treatment outcome in pregnant women followed up for 28 days (P = 0.018)." (PMID 28673292, 2017). "However, our ultimate aim is to include predictions of the outcome in patients with malaria using a disease‐specific virtual population incorporating physiological differences observed in patients with malaria, such as reduced CYP3A4 expression and changes in blood binding." (PMID 37587640, 2023). "The CYP3A4*1B and CYP3A4*3 status were not seen to influence the risk of malaria recurrence." (PMID 28934955, 2017). "Preliminary finding indicates that pharmacogenetic variation in CYP3A4 and CYP3A5 influences the LF plasma exposure and malaria treatment outcome in pregnant women." (PMID 28673292, 2017). "In light of the greater contribution of CYP3A4 to ivermectin metabolism rather than CYP3A5, it seems unlikely that pharmacogenetic differences between malaria endemic regions would be of importance." (PMID 37355605, 2023).
tuberculosis (13 papers, 2018 to 2025). A chronic, recurrent infection caused by the bacterium Mycobacterium tuberculosis. "Patients with tuberculosis with older age and genetic polymorphism of CYP3A4, CYP2C9, and CYP2C19 who received long-term rifampicin treatment were more likely to have antituberculosis drug-induced liver injury." (PMID 34872459, 2021). "Classic examples include the anti-HIV drug ritonavir (a CYP3A4 inhibitor) or the anti-tuberculosis drug rifampin (a CYP3A4 inductor)." (PMID 38657074, 2024). "Rifampin-based tuberculosis treatment was found to decrease lumefantrine exposure by 59%, which was expected, since rifampin is known to be a potent inducer of CYP3A4, and previous physiologically based pharmacokinetic modeling had predicted this in silico." (PMID 32071050, 2020). "Bedaquiline, an antimycobacterial agent approved for drug-resistant tuberculosis, is metabolized by CYP3A4, an hepatic enzyme strongly induced by rifampin, an essential part of drug-sensitive tuberculosis treatment." (PMID 29718967, 2018). "Additionally, tuberculosis is treated with combinations of antituberculosis drugs, including isoniazid, which is an inhibitor of CYP3A4." (PMID 37982585, 2024). "We hypothesize tuberculosis patients with genotyping CYP3A4 enzyme, CYP2C9 enzyme, and CYP2C19 enzyme are more likely to have ATB-DILI." (PMID 34872459, 2021). "Co-infection with talaromycosis and tuberculosis is common, with microbiology-confirmed tuberculosis coinfection seen in 22% of patients, and presents a therapeutic challenge in that rifampicin as a potent CYP3A4 inducer reduces itraconazole concentration by 60%." (PMID 29379703, 2018). "Specifically, rivaroxaban may not be safer than warfarin in sub-Saharan Africa as many sub-Saharan patients also receive P-glycoprotein and CYP3A4-modulating drugs for tuberculosis and HIV, drugs which have been reported to attenuate rivaroxaban’s advantage in terms of major bleeding risk." (PMID 35444556, 2022). "In the treatment of tuberculosis, BDQ is not administered concomitantly with rifampin because it is a substrate of CYP3A4, induced by rifampin, thus causing drug-drug interactions." (PMID 31964791, 2020).
lung carcinoma (12 papers, 2013 to 2025). "Our meta-analysis revealed an association between CYP3A4 (rs2740574) and lung cancer in the allelic, heterozygous, and dominant models." (PMID 38482381, 2024). "This conclusion can aid better personalized medicine for lung cancer management, while further assessment for genetic variants of CYP3A4, CYP27B1, CYP24A1, GC, and VDR is still required to address more robust evidence." (PMID 38482381, 2024). "Our work revealed that CYP3A4 (rs2740574) can represent an independent risk factor for lung cancer." (PMID 38482381, 2024). "CYP1A2 and especially CYP3A4 were selected for their relevance to metabolism of drugs used in treatment of lung cancer." (PMID 38370474, 2024). "The query indicated that sildenafil targets CYP3A4, which helps treat lung cancer." (PMID 40001634, 2025). "Current research demonstrates that sildenafil may serve as a potential agent for the treatment of lung cancer by inhibiting CYP3A4 through in vitro enzymatic assays, drug interaction investigations and pharmacokinetic studies." (PMID 38994794, 2024).
steatosis (12 papers, 2013 to 2024). Increased lipid within the cytoplasm of cells. "Additionally, in vitro experiments demonstrated that changes in CYP3A4 expression might be associated with free FA-induced steatosis." (PMID 35011625, 2021). "Other studies also reported decreased expression and activity of CYP3A4 in both human liver tissue with steatosis or non−alcoholic fatty liver disease development, which indicated the significance of CYP3A4 for liver health." (PMID 36496924, 2022). "The level of CYP3A4 protein expression was stable after induction of steatosis by free fatty acids indicating the retained differentiation state of the hepatocytes including capacity for drug metabolism by this clinically important cytochrome P450." (PMID 30250238, 2018). "Statistically significant correlations of hepatic CYP3A4-mediated clearance with body weight, steatosis, and NAS were observed for midazolam." (PMID 28649438, 2017). "The same trend was observed for all correlations, but only the relationship between CYP3A4 expression and steatosis showed a statistically significant correlation." (PMID 28649438, 2017). "However, our study suggests that increased CYP3A4 expression prevents LO2 cells from FFA-induced steatosis." (PMID 31191607, 2019). "CYP3A4 protein level was decreased in FFA-induced steatosis cells compared to control." (PMID 31191607, 2019). "Similarly, a significant decrease of CYP3A4 mRNA was observed in FFA-induced steatosis cells compared to control." (PMID 31191607, 2019). "Here, we investigated CYP3A4 expression in FFA-induced steatosis cells in vitro." (PMID 31191607, 2019). "Because of the importance of CYP3A4 activity in steatosis development, we then determined whether CYP3A4 mediated the regulatory effect of miR-200a-3p or miR-150-5p inhibitor on FFA-induced steatosis." (PMID 31191607, 2019). "To investigate whether decreased CYP3A4 in FFA-induced steatosis cells was due to miRNAs regulation, we used MicroInspector and TargetScan algorithms to screen antisense matches of CYP3A4 3′-UTR against human miRNAs." (PMID 31191607, 2019). "The objective of our work was to study the impact of periportal steatosis on pericentral drug metabolism focusing on the important CYP isoforms CYP1A2, CYP2D6, CYP2E1, and CYP3A4." (PMID 36528753, 2022). "Many studies indicated that the expression and activity of CYP3A4 decrease with the progression of steatosis, probably following the FGF21–PXR–CYP3A4 axis." (PMID 35011625, 2021). "More importantly, miR-200a-3p or miR-150-5p inhibitor reduced FFA-induced steatosis assessed by the BODIPY 493/503 staining, and this effect was abrogated by CYP3A4 gene silencing." (PMID 31191607, 2019). "Here, we found decreased CYP3A4 and increased miR-200a-3p and miR-150-5p in LO2 cells with free fatty acid (FFA)-induced steatosis." (PMID 31191607, 2019). "This suggested that miR-200a-3p or miR-150-5p inhibitor, through up-regulating CYP3A4, protected against FFA-induced steatosis." (PMID 31191607, 2019). "Here, we report that miR-150-5p and miR-200a-3p directly regulate CYP3A4 and are involved in free fatty acid (FFA)-induced steatosis." (PMID 31191607, 2019). "In this study, we reported two new CYP3A4 regulators, including miR-200a-3p and miR-150-5p, in FFA-induced steatosis." (PMID 31191607, 2019). "Here, we demonstrated that miR-200a-3p and miR-150-5p, through directly targeting 3′-UTR of CYP3A4, contributed to the development of FFA-induced steatosis in vitro." (PMID 31191607, 2019). "Periportal steatosis did also affect the pharmacokinetics of caffeine (CYP1A2) and midazolam (CYP3A4), but not of codeine (CYP2D6)." (PMID 36528753, 2022).
acute kidney injury (11 papers, 2012 to 2023). Sudden and sustained deterioration of the kidney function characterized by decreased glomerular filtration rate, increased serum creatinine or oliguria. "Preliminary results showed an increased incidence of acute kidney injury in the triple therapy group compared to a control group, which was possibly caused by a CYP3A4 drug interaction." (PMID 33974624, 2021). "Risk of adverse events such as acute kidney injury might occur following the coprescription of CYP3A4-metabolized statins and CCBs that inhibit CYP3A4." (PMID 26765458, 2016). "In conclusion, our study found the associated risks of acute kidney injury, hyperkalemia, acute myocardial infarction, and acute ischemic stroke were higher following the coprescription of CYP3A4-metabolized statins and CCBs that inhibit CYP3A4." (PMID 26765458, 2016). "The findings of our study demonstrated an increased risk of acute kidney injury, hyperkalemia, acute myocardial infarction, and acute ischemic stroke following the coprescription of CYP3A4-metabolized statins and CCBs that inhibit CYP3A4." (PMID 26765458, 2016). "Verapamil, clarithromycin, and voriconazole are known inhibitors of the CYP3A4 and their administration increased plasma concentration of everolimus (40 ng/ml –110 ng/ml) and its toxicities like mucositis, acute kidney injury, proteinuria or nephrotic syndrome." (PMID 37381038, 2023). "CYP3A4-inhibitors can raise the concentration of CCB and cause hypotension and even acute kidney injury (AKI)." (PMID 33971831, 2021). "Gandhi et al5 had reported acute kidney injury and hypotension due to CCB toxicity when CYP3A4 was inhibited." (PMID 26765458, 2016).
asthma (11 papers, 2006 to 2024). "In previous studies, CYP3A4 rs35599367 was associated with improved asthma control with glucocorticoid treatment." (PMID 39135792, 2024). "The expressions of PTGS1 and CYP3A4 were markedly increased in patients with rhinitis accompanied by asthma, while the expression of NR1I2 decreased synonym." (PMID 37741847, 2023). "Epigallocatechin gallate, a constituent of teas, has shown in vitro inhibition of Cytochrome P450 enzymes, including CYP1A2, CYP2C8, CYP2C9, and CYP3A4 and therefore has potential effects on the majority of conventional asthma drugs." (PMID 31998122, 2019). "The expression of CYP3A4 significantly correlated with Asthma, Graft-versus-host disease, Allograft rejection, Type I diabetes mellitus, Autoimmune thyroid disease, Ubiquitin mediated proteolysis, Cell cycle, Lysosome, Protein processing in endoplasmic reticulum, Hedgehog signaling pathway." (PMID 38239411, 2023). "Prior work demonstrated that the five most commonly prescribed glucocorticoids used in the treatment of asthma are metabolized by CYP3A enzymes, specifically CYP3A4, CYP3A5, and CYP3A710,11." (PMID 24555085, 2013).
Renal insufficiency (10 papers, 2012 to 2025). A reduction in the level of performance of the kidneys in areas of function comprising the concentration of urine, removal of wastes, the maintenance of electrolyte balance, homeostasis of blood pressure, and calcium metabolism. "Their metabolism is almost systematically hepatic via CYP3A4 and their pharmacokinetics are, therefore, little affected by renal insufficiency." (PMID 39481329, 2024). "Of note, all spindle poisons (taxanes and vinca-alkaloids) are metabolized in the liver via CYP3A4 mainly (docetaxel, vinorelbine) or partially (paclitaxel), and adaptation of these drugs in patients with renal insufficiency is generally not needed or is moderate." (PMID 39481329, 2024).